INS (insulin)
Diseases named in the same sentence as INS in open-access papers (continued):
Sharing a sentence is not in itself a finding about the gene and the disease.
Hyperglycemia (continued). "For instance, IR activates the sympathetic nervous system, leading to elevated adrenaline levels that inhibit insulin secretion and worsen hyperglycemia." (PMID 40977966, 2025). "These interventions are aimed at reducing hyperglycemia and improving insulin secretion and sensitivity." (PMID 40647906, 2025). "Clinically, this severity presents as an earlier age of onset and severe hyperglycaemia, often necessitating early insulin therapy." (PMID 40332430, 2025). "IR is characterized by reduced effectiveness of insulin in facilitating glucose uptake and utilization, along with downregulation of insulin-dependent glucose transporter proteins in peripheral tissues, thereby leading to stress-induced hyperglycemia." (PMID 40416376, 2025). "Hepatic selective IR: Weakened insulin suppression of hepatic glucose output leads to fasting hyperglycemia.Consequence: Excessive glucose supply to the body." (PMID 41244044, 2025). "Isorhamnetin ameliorates hyperglycemia and dyslipidemia, improves plasma insulin, and preserves islet architecture in STZ-induced T1DM, while being associated with metabolite remodeling enriched for arachidonic- and glycerophospholipid-linked pathways." (PMID 41156454, 2025). "It was also observed that it attenuated glucose intolerance (OGTT) in the mice fed with HFD+WB, suggesting that administration of this strain with FE activity improves insulin sensitivity and prevents hyperglycemia during the development of MS." (PMID 40710566, 2025). "Secondary endpoints analyzed show fewer episodes of rebound hyperglycemia after termination of the insulin infusion." (PMID 40978981, 2025). "Adiponectin is known to suppress the production of inflammatory cytokine by inhibiting pro-inflammatory signaling in macrophages, and it relieves hyperglycemia and improves insulin sensitivity by acting on muscle and liver." (PMID 41157128, 2025). "Current practice, therefore, aims for a blood glucose range of 140–180 mg/dL (7.8–10 mmol/L), treating persistent hyperglycemia with insulin while promptly correcting any hypoglycemia." (PMID 41441198, 2025). "The patient was taking more or less insulin than the prescribed dose, leading to alternating hypoglycemia and hyperglycemia." (PMID 41235379, 2025). "This pro-inflammatory environment causes insulin resistance in muscle, liver, and adipose tissue; as a consequence, β-cells continue the overproduction of insulin to control hyperglycemia until dysfunction of the pancreas occurs." (PMID 41011279, 2025). "DM is a chronic metabolic disease characterized by the hyperglycemia resulting from defects in insulin secretion, insulin action, or both." (PMID 40342327, 2025). "Adult Plk1PKO mice exhibit diabetic syndromes including hyperglycemia, glucose intolerance, and insulin hypersensitivity." (PMID 40879084, 2025). "Hyperglycemia leads to decreased PGH production, followed by a decline in insulin secretion, further worsening hyperglycemia in a self-propagating cycle." (PMID 40235646, 2025). "As the disease progresses, insulin secretion becomes insufficient to regulate glucose levels effectively, leading to persistent hyperglycemia." (PMID 40548186, 2025). "Diagnosis was based on a random blood glucose value > 11.1 mmol/L, a fasting blood glucose value > 7.7 mmol/L, or the requirement for hyperglycemia therapy with oral hypoglycemic agents or insulin following organ transplantation." (PMID 39941214, 2025). "He developed symptomatic hyperglycemia with worsening glycemic trend, requiring treatment with high-dose insulin and metformin." (PMID 39717432, 2025). "Overfeeding can manifest as hyperglycemia and increased insulin requirements, azotemia, elevated urea-to-creatinine ratio (UCR), and hypertriglyceridemia." (PMID 40416376, 2025). "In the management of AP, insulin therapy and glycemic control are essential therapeutic strategies, as hyperglycemia and IR are critical factors that exacerbate pancreatic injury and promote inflammatory responses." (PMID 40937420, 2025).
Hyperglycemia (continued). "In two hedgehogs, severe hyperglycemia improved as a result of subcutaneous injection of insulin (Humulin N Injection 100 unit, Lily Korea, Inc., Seoul, Republic of Korea) at a dose of 0.2 to 2 U/kg every 12 h." (PMID 40427332, 2025). "When we administer insulin to correct hyperglycemia, provide fluids to restore volume, and correct acidosis, hypokalemia can develop quietly and rapidly." (PMID 41255534, 2025). "(cornuofficinaliside F, neocornuside A, neocornuside F, etc.)stimulate glucose uptake in insulin-resistant HepG2 cells, potentially through transporter modulation that delays glucose absorption and reduces postprandial hyperglycemia." (PMID 41561166, 2025). "Diabetes mellitus is a group of metabolic disorders characterized by hyperglycemia due to defects in insulin secretion and/or action." (PMID 40517337, 2025). "Avoidance of hyperglycemia: Insulin is an effective treatment for hyperglycemia, but its impact on the risk of ROP remains controversial due to limited evidence." (PMID 40573070, 2025). "Even a lower dose of genistein (250 mg/kg for 4 weeks) ameliorated hyperglycemia, glucose tolerance, and insulin levels in STZ-induced diabetic mice, which was accompanied by improved β-cell proliferation, survival, and mass." (PMID 39861406, 2025). "Hyperglycemia also stimulates increased secretion of insulin by pancreatic β-cells, to obtain normoglycemia, resulting in hyperinsulinemia." (PMID 39859258, 2025). "One year pre-pregnancy, she was hospitalized for severe hyperglycemia (glucose, 300 mg/dL, hemoglobin A1c [HbA1c], 13%) with ketonuria, after improvement on insulin, she was switched to oral antihyperglycemic therapy, and self-discontinued follow-up." (PMID 41460436, 2025). "In an insulin-resistant state, the liver becomes less responsive to insulin, resulting in decreased glycogen synthesis and increased gluconeogenesis, thereby perpetuating hyperglycemia and abnormal lipid metabolism." (PMID 39920728, 2025). "Along similar lines, in an animal study, MOTS-c therapy was administeredto mice with gestational diabetes mellitus, which resulted in a significantimprovement in hyperglycemia, insulin sensitivity, and glucose tolerance." (PMID 41004666, 2025). "At hyperglycemia, plasma insulin was less (p < 0.05) for IUGR lambs than controls and was intermediate for IUGR+ω3 lambs." (PMID 40559370, 2025). "In summary, our data position ISO as a potential adjunct to insulin therapy by attenuating hyperglycemia while supporting β-cell integrity." (PMID 41156454, 2025). "Catecholamines enhance aerobic glycolysis, glycogen breakdown, and gluconeogenesis while inhibiting insulin-mediated glycogen synthesis, ultimately leading to hyperglycemia." (PMID 40308225, 2025). "The IRS1, identified in this study asdownregulated in the context of stress-induced hyperglycemia, plays a key role incellular glucose transport and insulin signaling." (PMID 40179269, 2025). "Another trial also found that a 6-month EPA treatment corrected hyperglycemia and postprandial insulin secretory ability among patients with IGM." (PMID 40302785, 2025). "Despite alteration in insulin dosage, the patient inexplicably showed episodes of hypo‐ and hyperglycemia." (PMID 41235379, 2025). "GLP-1RAs exert their effects by binding to receptors on pancreatic beta cells, activating intracellular signaling pathways that amplify insulin release in response to hyperglycemia." (PMID 40937349, 2025). "In other words, vast majority of women in the prediabetes group probably had subtle defects in insulin action and/or secretion but still had hyperglycemia." (PMID 41384021, 2025). "Initial labs showed hyperglycemia (1036 mg/dL), ketosis (beta-hydroxybutyrate 5.3 mmol/L), acidosis (pH 7.27), low insulin level (< 1.0), and low c-peptide (0.35 ng/mL)." (PMID 40612706, 2025).
Hyperglycemia (continued). "In T1D, the addition of pramlintide to meal-time insulin for 29 weeks reduced postprandial hyperglycemia, body weight, and daily insulin dose by 60%, 1.3 kg, and 28%, respectively, and improved oxidative stress." (PMID 39998445, 2025). "Chronic hyperglycemia not only affects the secretion and action of insulin but also leads to various tissue and organ dysfunctions." (PMID 41400625, 2025). "Reduced insulin activity results in perioperative hyperglycemia, suppressed protein synthesis, enhanced protein catabolism, and an increased risk of infection." (PMID 40502630, 2025). "As well, in hepatic IR, insulin, continues stimulating lipogenesis, which ends up producing hyperglycemia, hyperlipidemia, hepatic steatosis and T2DM." (PMID 39138826, 2025). "The OGTT curves revealed more severe hyperglycemia and a distinct insulin pattern in ObHH, consisting of blunted early secretion followed by prolonged hyperinsulinemia." (PMID 39885510, 2025). "Sirt activation specifically in liver of obese insulin-resistant mice significantly improved fatty liver, normalized hyperglycemia, as well as improved systemic insulin sensitivity." (PMID 40766326, 2025). "This process improves satiety, reduces postprandial hyperglycemia, and allows for a better match with insulin administration, thereby improving overall glucose control." (PMID 40641818, 2025). "Continuous glucose monitoring (CGM) systems equipped with ML (primarily RNNs and long short-term memory [LSTM] networks coupled with RFs) can predict glucose excursions and suggest insulin adjustments, reducing risks of severe hypoglycemia or hyperglycemia." (PMID 41002329, 2025). "The administration of rapid-acting insulin analogs 15–20 min before meals reportedly ameliorated postprandial hyperglycemia compared with administration immediately before meals in patients with type 1 diabetes." (PMID 39899133, 2025). "NDM should be high on providers’ differentials for a newborn with persistent hyperglycemia, as a faster insulin-to-sulfonylurea transition is preferred." (PMID 40309172, 2025). "It is marked by uncontrolled increases in blood sugar (hyperglycemia) due to impaired insulin secretion, defective insulin function, or both." (PMID 41228137, 2025). "IL-6 is subsequently released in large quantities, promoting hepatic glucose production, inhibiting insulin release, aggravating the occurrence of hyperglycemia and triggering an inflammatory storm." (PMID 40225322, 2025). "HCL systems, which partially automate insulin delivery, have demonstrated significant benefits in reducing both hyperglycaemia and hypoglycaemia in adults and children with type 1 diabetes." (PMID 41157817, 2025). "The first episode was triggered by cellulitis and metabolic acidosis, requiring high doses of IV insulin (600–800 IU/day) for less than 24 h; she was discharged after 1 week when her hyperglycemia stabilized." (PMID 41424588, 2025). "The association between insulin use and mortality observed in the retrospective study may reflect confounding by indication, as COVID-19 patients to whom insulin is applied are usually critically ill patients with severe hyperglycemia or comorbidities (e.g., cardiovascular disease)." (PMID 40469441, 2025). "There was a higher incidence of rebound hyperglycemia (>180 mg/dL) in the six hours after insulin discontinuation in the late glargine group, 63 (83%) vs. 35 (50%) (p<0.001)." (PMID 40978981, 2025). "In contrast, IGT is characterized by both early and late-phase insulin secretion defects alongside predominant skeletal muscle insulin resistance, resulting in prolonged hyperglycemia after glucose loading." (PMID 40375950, 2025). "Concomitant hyperglycemia denotes impaired insulin-mediated glucose disposal in skeletal muscle and adipose tissue." (PMID 41141345, 2025).
Hyperglycemia (continued). "Calcineurin inhibitors promote hyperglycemia by downregulating genes involved in enhancing insulin sensitivity in muscle tissue and by reducing GLUT-4 glucose transporters in muscle and adipose cells." (PMID 41155647, 2025). "This lipid–glucose dysregulation establishes a vicious cycle: IR exacerbates dyslipidemia and hyperglycemia, which in turn further impair insulin signaling and heighten β-cell stress." (PMID 41141345, 2025). "Postprandial hyperglycemia depends on several factors, such as quantity and composition of food, content of carbohydrate as well as production of insulin and inhibition of glucagon secretion." (PMID 39859258, 2025). "This has influenced clinical practice guidelines, leading to the broad adoption of an insulin basal-bolus regimen with a correctional scale as the standard of care for hyperglycemia in hospitalized patients." (PMID 39816910, 2025). "We discovered that the rats given an HFD plus fructose exhibited high body and visceral fat weight, SP, insulin insensitivity, hyperglycemia, and dyslipidemia." (PMID 40332475, 2025). "Insulin administration is effective for suppressing hyperglycemia and glucagon secretion, lipolysis, and ketogenesis, and it is recommended to start continuous infusion at 0.1 units/kg/hour." (PMID 40546498, 2025). "In recent years, several studies have reported that saffron supplementation can potentially reduce hyperglycemia and improve insulin sensitivity." (PMID 40842498, 2025). "GLP-1RAs improve hyperglycemia as well as the insulin sensitivity of the liver and global/local fat, thereby reducing the amount of lipotoxic metabolites and proinflammatory mediators in the circulation, contributing to hepatoprotection against MASLD and MASH." (PMID 39861190, 2025). "Physical activity (PA) can serve as a non‐pharmacologic strategy for hyperglycaemia management, lowering glucose through insulin‐independent mechanisms and enhancing insulin sensitivity, with experimental data demonstrating significant reductions in glucose." (PMID 41059660, 2025). "Chronic exposure to hyperglycemia suppresses β-cell function and reduces insulin biosynthesis and secretion while promoting apoptosis." (PMID 40666490, 2025). "Insulin suspension alone is often too slow to counteract rapid glucose declines, and relying on carbohydrate intake can lead to overshooting and rebound hyperglycaemia." (PMID 40718205, 2025). "Persistent hypercortisolemia likely drives this hyperglycemia through increased gluconeogenesis and insulin resistance." (PMID 41109933, 2025). "In older adult diabetic patients, depression can lead to apathy, impairing their ability to manage health, worsening hyperglycemia, and disrupting insulin metabolism." (PMID 40860530, 2025). "The state of hyperglycemia and increased insulin production can lead to endoplasmic reticulum (ER) stress, which can result in unfolded protein response (UPR) in β-cells." (PMID 39940862, 2025). "First, PA is known to enhance glycemic regulation by improving insulin sensitivity, mitigating hyperglycemia-induced nerve damage, and preventing the progression of diabetic neuropathy." (PMID 41267734, 2025). "Chronic subclinical inflammation aggravates hyperglycemia by regulating insulin resistance and leads to a series of diabetic complications." (PMID 40283466, 2025). "The mechanisms by which hyperglycemia, elevated plasma insulin concentrations, and individual anti-diabetic medications influence AAA pathophysiology remain poorly understood." (PMID 40502134, 2025). "This also allows for the verification of the meal dose of insulin and a decrease in postprandial hyperglycemia." (PMID 40244115, 2025). "Interventions include a very low-fat diet, insulin therapy if hyperglycemia is present, and in select cases, plasmapheresis." (PMID 41012446, 2025).
Hyperglycemia (continued). "Upon logging in, users can create diary entries that record their current blood glucose levels and track instances of hypoglycemia and hyperglycemia, carbohydrate intake, insulin injections, and physical activities." (PMID 40865093, 2025). "Type 1 diabetes (T1DM) is an autoimmune disease characterized by hyperglycemia secondary to pancreatic beta cell destruction leading to insufficient insulin production." (PMID 40004164, 2025). "Individuals with MetS typically exhibit impaired insulin responses in adipose tissue, liver, and skeletal muscles, which contribute to hyperglycemia." (PMID 40332518, 2025). "Studies have demonstrated their capacity to enhance insulin secretion from pancreatic β-cells, reduce postprandial hyperglycemia, and inhibit the activation of nuclear factor-kappa B (NF-κB), a key regulator of inflammatory responses." (PMID 40563357, 2025). "An international consensus meeting on management of PTDM recommended the use of early exogenous insulin administration for treatment of postoperative hyperglycemia after transplantation to prevent PTDM." (PMID 41268027, 2025). "This apparent contradiction is clinically significant, as it necessitates frequent insulin dose adjustments and close monitoring to avoid both hyperglycemia and hypoglycemia extremes." (PMID 41040769, 2025). "The larger decrease observed in our population (−3%) is likely attributable to higher baseline hyperglycemia and delayed insulin initiation in Indonesia, where insulin is often started late in the disease course." (PMID 41293743, 2025). "Existing treatments, such as oral antidiabetic drugs, antihyperglycemic agents, and exogenous insulin injections, temporarily improve insulin sensitivity in tissues or mitigate hyperglycemia-related symptoms." (PMID 39851765, 2025). "This is due to glucose freely passing through the placenta; therefore, maternal hyperglycemia associated with GDM results in elevated glucose levels in the fetus, causing excess fetal insulin production, termed hyper-insulinism." (PMID 39913386, 2025). "NGS helped switch the management of hyperglycemia from unnecessary insulin injections to glibenclamide in 8 of our patients with KCNJ11 mutations." (PMID 39504571, 2025). "The antirheumatic drug leflunomide, also an AhR agonist, demonstrates potential antidiabetic effects by enhancing insulin sensitivity and reducing hyperglycemia, likely mediated through its AhR-dependent anti-inflammatory properties." (PMID 41440753, 2025). "On the other hand, epicatechin lowered hyperglycemia and improved insulin response to a glucose load, possibly by modulating pancreatic insulin production and secretion in rats." (PMID 39861406, 2025). "Diabetes mellitus is a metabolic disorder characterized by persistent hyperglycemia, primarily resulting from defective insulin secretion or impairment biological action." (PMID 41035908, 2025). "Lipid metabolism disorders result in fat accumulation in the liver, muscles, and blood vessel walls, affecting the normal role of insulin and resulting in IR, which is more likely to induce or aggravate hyperglycemia." (PMID 40290429, 2025). "Although individual results differ, studies have shown improvements in time to resolution of DKA, insulin infusion time, intensive care unit (ICU) length of stay, hospital length of stay, and rebound hyperglycemia after the insulin infusion is stopped." (PMID 40978981, 2025). "Chronic hyperglycaemia results from elevated blood glucose levels due to disturbed insulin secretion and/or action." (PMID 41179869, 2025). "CGMSs can also aid in identifying asymptomatic hypoglycemia or hyperglycemia, ultimately enhancing insulin therapy for each dog." (PMID 40723467, 2025). "Concurrently, Inflammation also reduces insulin sensitivity, exacerbating hyperglycemia and further promoting inflammatory responses, creating a vicious cycle of renal damage, tubulointerstitial injury, fibrosis, and worsening kidney function." (PMID 40115740, 2025).